NFIA (nuclear factor I A)
Description:
Recognizes and binds the palindromic sequence 5'-TTGGCNNNNNGCCAA-3' present in viral and cellular promoters and in the origin of replication of adenovirus type 2. These proteins are individually capable of activating transcription and replication.
Synonyms: NF1-A; CTF; NF-I/A; NFI-A; KIAA1439; NFI-L; BRMUTD; C1DELp32p31; DEL1P32P31
Tractability: PROTAC: ubiquitination databases record sites on it; its protein half-life has been measured.
Gene: Protein-coding gene on chromosome 1 (60,865,259 to 61,462,788, forward strand). Ensembl gene ENSG00000162599.
Subcellular location: Nucleus
Subcellular location (Human Protein Atlas): Nucleoplasm
Pathways (Reactome):
Gene expression (Transcription): RNA Polymerase III Abortive And Retractive Initiation; RNA Polymerase III Transcription Termination
Gene Ontology:
Molecular function: DNA-binding transcription activator activity, RNA polymerase II-specific; DNA-binding transcription factor binding; RNA polymerase II cis-regulatory region sequence-specific DNA binding; DNA-binding transcription factor activity; DNA-binding transcription factor activity, RNA polymerase II-specific; chromatin binding; DNA binding
Biological process: positive regulation of transcription by RNA polymerase II; regulation of DNA-templated transcription; regulation of transcription by RNA polymerase II; viral genome replication; BMP signaling pathway; cartilage development; cell morphogenesis; limb morphogenesis; positive regulation of DNA-templated transcription
Cellular component: nucleoplasm; nucleus; chromatin
Genetic constraint (gnomAD): Loss-of-function variants: 5 observed, 60.24 expected, observed/expected ratio (o/e) 0.083, 90% interval 0.042 to 0.17. The upper end of that interval is the gene's LOEUF score, 0.17, which puts it in group 1 of 6, group 1 being the genes least tolerant of losing a copy. Missense variants: 398 observed, 651.59 expected, observed/expected ratio (o/e) 0.61, 90% interval 0.56 to 0.66. Synonymous variants: 230 observed, 242.72 expected, observed/expected ratio (o/e) 0.95, 90% interval 0.85 to 1.06.
Gene-disease validity (ClinGen):
ClinGen rates the evidence that NFIA causes each of these diseases.
brain malformations with or without urinary tract defects (autosomal dominant): Definitive.
Homologues: Orthologues: chimpanzee NFIA (100% identical), dog NFIA (100% identical), macaque NFIA (100% identical), pig NFIA (100% identical), rabbit NFIA (100% identical), mouse Nfia (99% identical), guinea pig NFIA (98% identical), rat Nfia (98% identical), tropical clawed frog nfia (96% identical), zebrafish nfia (92% identical), Drosophila melanogaster NfI (48% identical), Caenorhabditis elegans nfi-1 (38% identical). Paralogues in human: NFIX (71% identical), NFIC (65% identical), NFIB (60% identical).
Diseases named in the same sentence as NFIA in open-access papers:
NFIA is named in the same sentence as 109 diseases in open-access papers, as found by Europe PMC text mining. Sharing a sentence is not in itself a finding about the gene and the disease. The quoted sentences say what the papers report.
glioma (15 papers, 2011 to 2025). A benign or malignant brain and spinal cord tumor that arises from glial cells (astrocytes, oligodendrocytes, ependymal cells). "DER enhancer‐associated genes, including PDGFRA and NFIA, have been linked to the tumourigenicity of glioma models and/or neural progenitor cell fate decisions." (PMID 34767259, 2022). "Roles for NFIA and NFIB as tumor suppressors in glioma have been documented, and expression of these two factors is inversely correlated with tumor grade such that higher grade tumors are associated with lower expression of NFIA or NFIB." (PMID 34012965, 2021). "This NFIA/SMC4 regulatory axis represents a potential therapeutic target for glioma and underscores the importance of transcriptional networks in gliomagenesis." (PMID 40933894, 2025). "Regarding NFI role in glioma therapy, NFIA has been identified to undergo regulation from microRNA miR-302b, which decreases glioma cell survival." (PMID 35409080, 2022). "Studies in a mouse model of malignant glioma show that SOX10 is not sufficient to induce glioma tumorigenesis, likely due to the cross inhibitory relationship of SOX10 and NFIA that is present in development and is conserved during tumorigenesis in glioma." (PMID 34012965, 2021). "RP5-833A20.1 inhibits cell proliferation, metastasis and cell cycle progression by suppressing NFIA in glioma." (PMID 29552296, 2018). "According to our results, we conclude that inhibition of NFIA-mediated IGFBP2 signaling plays a crucial role in miR-302b-induced glioma U87-MG cell death." (PMID 28323865, 2017). "We identified that NFIA-mediated IGFBP2 signaling pathways are involved in miR-302b-induced glioma cell death." (PMID 28323865, 2017). "NFIA-activated IGFBP2 expression also exhibited antagonistic effects on miR-302b-induced glioma cell apoptosis." (PMID 28323865, 2017). "Because IGFBP2 is a well-established tumor-promoting factor in glioma, we investigated the role of NFIA in the regulation of IGFBP2 gene expression in glioma growth." (PMID 28323865, 2017). "To investigate the role of NFIA in glioma growth, we compared the endogenous protein levels of NFIA in normal astrocytes and three glioma cell lines." (PMID 28323865, 2017). "Since NFIA specifically has been shown to be significantly involved in Glioma tumorigenesis we hypothesized NFIA to be the primary CARM1 substrate responsible for regulating NGFR signaling in GSCs." (PMID 40321217, 2025). "Additionally, the “ErbB Signaling Pathway,” “Tight Junction,” “Glioma,” and “Small Cell Lung Cancer” pathways are also prominently represented, further highlighting the broad regulatory impact of NFIA, NFIB, NFIC, and NFIX on several types of cancer." (PMID 39617063, 2025). "Additionally, miR-223 has been reported to downregulate NFIA expression and, ultimately, suppress glioma cell proliferation." (PMID 35409080, 2022). "Hence, this particular miRNA seems to function through a regulatory loop that involves NFIA/IGFBP2 inhibition in order to induce death of glioma cells." (PMID 35409080, 2022). "Moreover, ectopic expression of NFIA or NFIB in a glioma xenograft model is sufficient to promote differentiation of tumor cells." (PMID 34012965, 2021). "Furthermore, the antagonistic relationship between NFIA and Sox10 regulates the diversification of glial lineages and glioma subtypes." (PMID 28323865, 2017). "Nuclear factor IA (NFIA), higher levels of which were significantly related to poor survival, was identified as a direct target gene of miR-302b and was involved in miR-302b-induced glioma cell death." (PMID 28323865, 2017). "High protein levels of NFIA were found in glioma cells, particularly U87-MG cells." (PMID 28323865, 2017).
glioma (continued). "Similarly, in the present study, we found that miR-302b induced glioma cell death by targeting and inhibiting NFIA expression." (PMID 28323865, 2017). "Moreover, NFIA-regulated IGFBP2 signaling pathways play a critical role in the ability of miR-302b to regulate apoptosis in glioma cells." (PMID 28323865, 2017). "In glioma cells, the miR-223/NFIA axis suppressed glial precursor proliferation and tumorigenesis." (PMID 28323865, 2017). "Like NFIB, NFIA and NFIX also have been implicated in glioma." (PMID 27083054, 2016). "In a glioma cell line, NFIA and NFIC siRNAs inhibited and enhanced FABP7 promoter activity, respectively, thus indicating that FABP7 promoter activity in RCC cell lines may be weaker than that in the HEK293 cell line." (PMID 21771320, 2011). "In addition, NFIA is also a target of miR-223, which suppresses the proliferation of glial precursors via repression of NFIA in the CNS development; the miR-223/NFIA axis inhibits tumorigenesis in a human glioma cell line." (PMID 28481269, 2017). "Interestingly, the oncogenic effect of NFIB in neural GBM is akin to the action of NFIA in maintaining the glial progenitor cell pool in the embryonic spinal cord and perhaps analogously promotes the propagation of the glioma stem cell compartment in this subtype." (PMID 27083054, 2016). "Interestingly, NFIA also can behave as either a tumour suppressor or an oncogene in glioma." (PMID 27083054, 2016). "The SRRS and nomogram provide robust tools for prognosis and personalized therapy, supporting the NFIA/SMC4 axis and downstream effectors as potential therapeutic targets for glioma." (PMID 40933894, 2025). "The IHC results corroborated the positive correlation between NFIA and SMC4 expression levels, showing a consistent trend in the human glioma specimens." (PMID 40933894, 2025). "SMC4 drives glioma progression through dual mechanisms TGF-β/SMAD-mediated metastasis and LDHA-dependent glycolysis regulated by NFIA." (PMID 40933894, 2025). "Bioinformatics analyses reveal a strong positive correlation between NFIA and SMC4 in glioma datasets, validated by co-expression in clinical specimens." (PMID 40933894, 2025). "Recently, the direct roles of NFIA and OLIG2 in tumor development in glioma mouse models were also tested." (PMID 32573857, 2020). "Both NFIA and IGFBP2 levels were higher in glioma cell lines and tumor tissues and were significantly associated with a poor survival rate." (PMID 28323865, 2017). "NFIA, identified as the CCAAT box element-binding transcription factor, is necessary to promote glial development and glioma tumorigenesis." (PMID 28323865, 2017). "Consequently, our data suggest that NFIA enhances the IGFBP2 signaling pathway, resulting in glioma tumorigenesis." (PMID 28323865, 2017). "This discrepancy might be attributed to a difference in FABP7 promoter regulation of NFIA and NFIC in RCC cell lines and glioma cell lines." (PMID 21771320, 2011).
osteosarcoma (8 papers, 2017 to 2025). A usually aggressive malignant bone-forming mesenchymal neoplasm, predominantly affecting adolescents and young adults. "For instance, lncRNA LIFR-AS1 sponges miR-29a to upregulate NFIA, thereby promoting osteosarcoma cell proliferation." (PMID 40696350, 2025). "In the present study, we find that miR-29a is lowly expressed in osteosarcoma tissues compared with normal tissues, and it can inhibit the progression of osteosarcoma cells via targeting NFIA." (PMID 33794884, 2021). "The expression of NFIA was examined in human primary osteosarcoma tissue and corresponding lung metastases (n = 10 pairs), and the result showed that NFIA was expressed more strongly in pulmonary metastasis focuses." (PMID 33794884, 2021). "Then, the expression of NFIA protein was detected by western blot, and the result indicated that NFIA was highly expressed in osteosarcoma cell lines (143B, HOS, MG63, MNNG, Saos2 and U2OS) compared with human osteoblast cell Line hFOB." (PMID 33794884, 2021). "Macrophage-derived exosomal lncRNA LIFR-AS1 can promote osteosarcoma cell proliferation, invasion, and restrain apoptosis via the miR-29a/NFIA axis." (PMID 34295338, 2021). "Taken together, macrophages-derived exosomal lncRNA LIFR-AS1 can promote osteosarcoma cell proliferation, invasion, and restrain cell apoptosis via miR-29a/NFIA axis, which can act as a potential novel therapeutic target for osteosarcoma therapy." (PMID 33794884, 2021). "Flow cytometry results showed that miR-29a could induce apoptosis of osteosarcoma cells, and NFIA-knockdown could recover miR-29a inhibitor-mediated apoptosis inhibition." (PMID 33794884, 2021). "The results of cck-8, colony formation and EdU assays showed that miR-29a significantly inhibited the proliferation of osteosarcoma cells, and NFIA-knockdown could partially reverse miR-29a inhibitor-mediated cell proliferation promotion." (PMID 33794884, 2021). "Correspondingly, NFIA-knockdown could partially reverse the tumor inhibition effect of miR-29a on osteosarcoma cells." (PMID 33794884, 2021). "NFIA is highly expressed in osteosarcoma patients with pulmonary metastasis, and LIFR-AS1 can be promoted through the miR-29a/NFIA axis." (PMID 35071590, 2022). "Besides, the results of the wound-healing assay and transwell assay demonstrated that miR-29a significantly inhibited the migration and invasion abilities of osteosarcoma cells, and NFIA-knockdown could recover miR-29a inhibitor-mediated cell migration promotion and invasion promotion." (PMID 33794884, 2021). "In conclusion, our results revealed that macrophages-derived exosomes played an important role in osteosarcoma development and macrophages-derived exosomal lncRNA LIFR-AS1 promoted osteosarcoma cell proliferation and invasion via miR-29a/NFIA axis." (PMID 33794884, 2021). "Furthermore, western blot results showed that miR-29a significantly inhibited the expression of NFIA, anti-apoptosis protein Bcl-2, and EMT marker N-cadherin, but promoted the expression of pro-apoptotic protein Bax and EMT marker E-cadherin in osteosarcoma cells." (PMID 33794884, 2021).
prostate carcinoma (7 papers, 2017 to 2025). A carcinoma that arises from epithelial cells of the prostate gland. "miR-215-5p, for example, inhibits prostate cancer metastasis by targeting PGK1, whereas miR-671-5p increases prostate cancer metastasis by targeting the NFIA/CRYAB axis." (PMID 36884182, 2023). "In the TCGA database, NFIA, NFIB and NFIC mRNA levels were significantly downregulated in prostate cancer patients." (PMID 32219034, 2020). "Moreover, ATAC-seq data suggest similar roles for NFIA and NFIB in the SHH subgroup of medulloblastoma, NFIB, and NFIX in prostate cancer, respectively." (PMID 39617063, 2025).
developmental delay (6 papers, 2016 to 2021). "Haploinsufficiency of the NFIA gene is expected to cause an abnormal corpus callosum, ventriculomegaly or hydrocephalus, developmental delay, tethered spinal cord, Chiari I malformation, seizures, urinary tract defects, and craniofacial anomalies." (PMID 26997977, 2016). "All six patients who have NFIA nonsense or frameshift mutation have been reported to have macrocephaly, five patients showed abnormalities of corpus callosum, hydrocephalus or ventriculomegaly, and developmental delay." (PMID 32926563, 2020). "In addition, in two patients (patients 3,5) the translocations disrupted NFIA and ATP7A, which are a known cause of developmental delay and Menkes disease, respectively." (PMID 32344861, 2020). "Similarly, the patient having a smaller microdeletion encompassing NFIA displayed only three of the clinical features as a result of NFIA deletion, namely abnormal corpus callosum, ventriculomegaly and developmental delay." (PMID 26997977, 2016).
glioblastoma (6 papers, 2015 to 2025). The most malignant astrocytic tumor (WHO grade IV). "Overexpression of NFIA has been reported in esophageal squamous carcinoma and Glioblastomas and plays a tumor-promoting role." (PMID 33794884, 2021). "Another study demonstrated that activation of NFκB signaling directly enhanced the transcription of NFIA in glioblastoma cells." (PMID 29577671, 2018). "Because a previous study suggested that NFIA promotes glioblastoma growth, we focused on the effects of miR-302b on NFIA gene expression." (PMID 28323865, 2017). "To dive deeper into a single NFI and illustrate the ability of our datasets to inform new biological insights, we examined the NFIA interactome in the U251 malignant glioma cell line due to the critical role of NFIs in glioblastoma and compared it to the HEK293 interactome." (PMID 39617063, 2025). "For example, while both NFIA and NFIB are required for in vitro and in vivo glioblastoma growth, NFIA overexpression leads to cell proliferation and migration, whereas NFIB suppresses tumor growth and promotes glial differentiation." (PMID 39617063, 2025). "The identification of a regulatory loop whereby miR-302b inhibits NFIA, leading to a decrease in expression of IGFBP-2, may provide novel directions for developing therapies to target glioblastoma tumorigenesis." (PMID 28323865, 2017).
Intellectual disability (5 papers, 2016 to 2024). "In particular, NFIB K126E mutation (at the site corresponding to K125 residue in NFIA) causes a severe loss of transcriptional activity and is one of the variants associated with intellectual disability and macrocephaly." (PMID 33973697, 2021). "In this article, we report the recurrent heterozygous missense mutation K125E in the NFIA gene in two unrelated patients with an intellectual disability, corpus callosum anomaly, and macrocephaly." (PMID 33973697, 2021). "We propose six candidate genes (DAB1, HOOK1, DOCK7, DNAJC6, PDE4B, and NFIA) for the clinical features such as intellectual disability and OCD observed in DGDP005, because each of these genes is involved directly or indirectly in neurological disorders." (PMID 26997977, 2016). "Among these five DECIPHER cases, DCP288170 with an intragenic deletion within NFIA, displayed intellectual disability." (PMID 26997977, 2016). "Interestingly, we also observed that 28 genes actively expressed at this stage, including genes such as NFIA, CDH13, TCF4, and DLG2, were associated with intellectual disabilities, autism spectrum disorders, irritability, and depression." (PMID 39452151, 2024). "Importantly, one patient with an intragenic microdeletion within NFIA and an additional patient with a balanced translocation disrupting NFIA display intellectual disability coupled with macrocephaly." (PMID 26997977, 2016). "We propose NFIA is responsible for intellectual disability coupled with macrocephaly, and microdeletions at 1p31.3p32.2 constitute a contiguous gene syndrome with several genes contributing to syndromic intellectual disability." (PMID 26997977, 2016). "Indeed, the NFIA transcript levels were markedly reduced in DGDP005 suggesting that NFIA may be contributing to syndromic intellectual disability." (PMID 26997977, 2016). "We also determined the transcript levels of six candidate genes (DAB1, HOOK1, NFIA, DOCK7, DNAJC6 and PDE4B) for syndromic intellectual disability." (PMID 26997977, 2016). "Comparative deletion mapping showed that there are at least six candidate genes including, NFIA, HOOK1, DOCK7, DAB1, DNAJC6, and PDE4B, that could contribute to the syndromic or non-syndromic intellectual disability." (PMID 26997977, 2016). "Particularly, the gene NFIA was found to be affected by a heterozygous intragenic deletion in two patients; its haploinsufficiency is considered a main driver to the phenotypes resulting of the chromosome 1p32-p31 deletion syndrome (OMIM #613735), especially macrocephaly and intellectual disability." (PMID 36553552, 2022).